IL1B (interleukin 1 beta)
Diseases named in the same sentence as IL1B in open-access papers (continued):
Sharing a sentence is not in itself a finding about the gene and the disease.
infection (continued). "The results demonstrate that the expression of IL-1β reached a peak at 36 hpi in the PRRSV-associated infection groups, and the expression of IL-1 β was most obviously up-regulated in the PRRSV–PCV2 group." (PMID 36992486, 2023). "Dysregulation of pro-inflammatory cytokines (TNF-α, IL-1β and IL-6) and anti-inflammatory cytokines (IL-10) are often associated with life-threatening infection or presence of endotoxin." (PMID 37424774, 2023). "Pyroptosis has at least three consequences; it allows the release of pro-inflammatory cytokines, such as IL-1β, and IL-18, eliminates the replicative niche of pathogens upon infection and causes cell death." (PMID 37771587, 2023). "Breakthrough infection after vaccination with a low dose of adenoviral vectored Spike protein prevents hippocampal production of IL-1β during breakthrough SARS-CoV-2 infection, loss of neurogenesis, and subsequent memory deficits." (PMID 37790551, 2023). "Transcript levels of IL-18 and IL-1β were significantly increased in liver tissues after WT W24 infection, and this consequence was similar to that caused by LPS injection." (PMID 36977062, 2023). "Further studies exhibited that PRU tachyzoites infection caused an enhanced IL-1β response when NF-κB signaling was preactivated by LPS in BMDCs." (PMID 36214572, 2022). "SARS-CoV-2 D614G- and Delta- variant infection induced production of inflammatory cytokines, including high-level of IL-2, GM-CSF, KC at day 3 pi and IL-1β, TNF-α, IL-2, IL-4, IL-6, KC (Neutrophil chemoattractant) at day 7 pi." (PMID 35734088, 2022). "Casp-1 deficiency (Casp-1−/−) caused a significant decrease in IL-1β production (green lines), while IL-1α secretion as well as the level of cell death remained unaffected during infection with all three Rickettsia spp." (PMID 35130729, 2022). "Expression of genital IL-1β has been associated with inflammation and symptomatic infection and was significant in disease progression." (PMID 38323170, 2022). "We performed further analysis by measuring the associated cytokine IL-1β level in the supernatant of WT and Caspase 11-/- BMDMs 12 hours post infection." (PMID 36318583, 2022). "Infection with HAdV35 caused increased expression of IL-6, IL-1β, TNF-α, and especially IL-8 in both A549 and SK-OV-3 cells." (PMID 35458402, 2022). "The infection caused by APEC in this study led to a significant increase in the expression of IL-1β, IL-6 and TNF-α mRNA in mice brains." (PMID 35900973, 2022). "In agreement, only IL-1β was statistically significantly associated with the odds ratio early in infection." (PMID 36248831, 2022). "After infection of THP-1 cells with S. mutans there was an increase in the inflammasome expression associated with IL-1β secretion through activation of caspase-1, NLRP3, and NLR family CARD domain-containing 4 (NLRC4)." (PMID 35893249, 2022). "The production of IL-1β is associated with the upregulation of lysophosphatiylcholine (LPC) in microglial cells upon infection by ZIKV." (PMID 35371036, 2022). "Pro-inflammatory cytokines such as the TNF-α and IL-1β have been shown to mediate host immune function and produce an immune response quickly after pathogenic microorganisms infection." (PMID 35236420, 2022). "While, in the condition of infection, M. oleifera mainly acted to reduce the A. hydrophila-associated inflammatory and degenerative changes by downregulating the expression level of IL-1β, IL-8, and IFN-γ." (PMID 35812877, 2022). "A study comparing the outcome of infection by Staphylococcus aureus in susceptible and resistant mice concluded that the levels of pyroptosis and the pro-inflammatory cytokine IL-1B were higher in susceptible mice." (PMID 35400946, 2022). "We found that FXR deficiency in hepatocytes promoted the progression of liver injury, aggravated weight loss and death caused by infection, and promoted inflammatory cytokines production, such as IL-6, IL-1β, TNF-α, IL-4, IL-10, and IL-13." (PMID 35930537, 2022).
infection (continued). "had also found that IL-1β was upregulated in infections caused by various Legionella species, further indicating its importance in infection." (PMID 36159650, 2022). "In this work, similar to our previous report, we demonstrated that HPV infection promotes chronic inflammation through high levels of IFN-γ, IL-1β and IL-6 caused by single or multiple infection, and even an increment of IL-4, as in a preliminary study." (PMID 35739948, 2022). "IL-1β over production was also observed in β-B.1.351 (South Africa) infected-MDM at 24h post-infection in comparison to the other SARS-CoV-2 variants and uninfected MDM (all p<0.0001), respectively." (PMID 36601113, 2022). "While it has been proposed that IL-1β is a master regulator of early inflammatory and immune responses to infection, high and/or persistent increases in IL-1β have been associated with immune dysfunction and disease." (PMID 36026499, 2022). "Further analysis of the secretion of pro-IL-1β showed that the level of IL-1β was positively associated with the level of infection." (PMID 35871079, 2022). "We specifically show that different possible inflammatory states in BV are either associated with persistence of HR-HPV infection (i.e., IL-1β/IP-10) or the progression of infection to precancer (i.e., TNF-α/MIP-1β)." (PMID 35017496, 2022). "The infection caused the overexpression of interferon and pro-inflammatory cytokines, such as IL-1β, TNF-α, and IL-8." (PMID 35385544, 2022). "Higher levels of expression of il-1β have been associated with infections with ectoparasites, virus, and exposure to bacterin derivate from Y. ruckeri." (PMID 35328519, 2022). "Infections caused by pathogens are usually accompanied by a surge in pro-inflammatory cytokines, such as IL-1β and IL-6." (PMID 35602082, 2022). "Studies have shown that the expression of inflammatory factors IL-1β and IL-6 in cells is higher than that of fimbriae-deficient strains after infection with wild-type Salmonella." (PMID 36431853, 2022). "There is evidence that blocking IL-1β signaling can reduce postoperative pain, but completely blocking IL-1β signaling can increase infection risk and reduce effective wound healing." (PMID 34408803, 2021). "Infection of BMDM with Δmag1 parasites induced a significant increase in interleukin 1β (IL-1β) secretion, which is a hallmark of inflammasome activation." (PMID 34006649, 2021). "IRGB10-deficient mice, which are defective in caspase-1 activation and IL-1β release, were also shown to be susceptible to infection." (PMID 33735255, 2021). "The production of mature IL-1β is linked to Warburg metabolism in mice and to the ability of human macrophages to increase glycolysis in response to infection with Mtb." (PMID 34691015, 2021). "In numerous in vitro and in vivo studies, proinflammatory signals, such as TNF-α, IL-1β, and IL-6, have been implicated in deviating immune responses to infection with S. aureus and E. coli." (PMID 34222051, 2021). "The finding is particularly interesting especially when we analyze the literature across different pathogenic NWHs infections that show stronger pro-inflammatory cytokine profiles characterized by IFNγ, TNFα, high levels of IL-6 as well as IL-1β." (PMID 33815363, 2021). "Among the L. pneumophila-induced cytokines impacted by TLR3 and/or TLR4, IL-6 and IL-1β are associated with increased neutrophil infiltration to sites of infection." (PMID 34280250, 2021). "During infection, the expression of IL-1β, IL-6, TNF-α, and iNOS in the Glu deficiency group was significantly decreased compared with the APEC XM infection group." (PMID 34502151, 2021). "IL-1β activates and regulates early responses to infection, activates NF-kB, and is associated with the onset of spontaneous preterm birth." (PMID 34959801, 2021). "Although the anti-IL-1β strategy is successful in preventing recurrent cardiovascular events, it is associated with a higher incidence of fatal infections as shown in the CANTOS trial." (PMID 34210954, 2021).
infection (continued). "Chromatin accessibility for pro-inflammatory and infection-associated genes such as Il1b, Il6, Nlrp3, Itgam (Cd11b), CD80, CD14, Fos, and Jun were also increased in infected AMs and IMs (cluster 5)." (PMID 34292313, 2021). "IL-1β, which is mainly generated at the injury or infection sites, induces inflammation-associated gene expression, such as cyclooxygenase-2 and inducible nitric oxide synthase to produce prostaglandin E2 and nitric oxide, respectively." (PMID 33686176, 2021). "Infection with mCoV-A59 caused robust activation of inflammasome as measured by cleavage of active IL-1β (p17) in BMDM supernatants as well as in cell lysates." (PMID 34151773, 2021). "In mouse bone marrow-derived macrophages (BMDM), infection with Δmag1 parasites induced a significant increase in IL-1β secretion, which is a hallmark of inflammasome activation." (PMID 34006649, 2021). "IL-1β is a potent proinflammatory mediator implicated in recruiting immune cells to the site of infection and stimulating adaptive immune responses, and IL-18 induces the sequential activation of natural killer cells and cytotoxic T cells." (PMID 34943932, 2021). "NLRP3 inflammasomes respond to various risk states of the body (including infection and metabolic disorders) after inflammatory factors (IL-1β, IL-18) are released, mainly causing lung injury." (PMID 33954183, 2021). "Our findings of increased IL-1β levels were consistent with those observed in infections caused by S. aureus and S. epidermidis." (PMID 33665221, 2021). "The upregulation of TNFα, IL6, IL1β, and IFNγ was reported as inflammatory cytokines associated with the postviral infection, which played a role in the recruitment of more immune cells for defense against the virus." (PMID 34074129, 2021). "The impact of AIM2 deficiency in the secretion of IL-1β by macrophages infected with isolate 4I2 was more pronounced than that seen in the case of infection with 6C4." (PMID 32327653, 2020). "Pulmonary inflammation in mice after infection with A. baumannii has been associated with IL-1β production and the severity of lung pathology." (PMID 33329595, 2020). "IL-1β selectively expands and sustains IL-22 producing immature natural killer cells, and IL-22 is linked to Type 3 immune responses during infections of extracellular bacteria and fungi." (PMID 32961074, 2020). "We found that for IL-1β, transcription levels after infection were significantly associated with age." (PMID 33121170, 2020). "This difference is potentially important, as IL-1β is significantly elevated in CF and has a wide range of biological effects, associated with both infection and inflammation." (PMID 32118580, 2020). "Based on our results, it appears that Meth mediated increased IL-1β expression acts to prime cells to be more susceptible to infection with HIV-1." (PMID 32117283, 2020). "Anakinra: (antagonist of IL-1β) the inhibition of IL-1β reduces the cytokine storm caused by infection." (PMID 32550705, 2020). "IL-1β, a leukocytic pyrogen, can cause a number of different autoinflammatory reactions during infection." (PMID 32536938, 2020). "Inhibition of NLRP3 or caspase-1 during infection of macrophages with the severe TB causing isolate (6C4) also decreased IL-1β secretion." (PMID 32327653, 2020). "Increased IL-1β level was evident in bronchoalveolar lavage fluid from CF patients with infection and this increase has been temporally associated with a clinical response to treatment." (PMID 32817626, 2020). "We found that cDC2s, and at later time points also moDCs, secrete similar levels of IL-1β, IL-8, and TNFα upon infection with the wt and the CagPAI-deficient strain." (PMID 32486097, 2020). "From the pathogen’s perspective, M. tuberculosis isolates that trigger high IL-1β responses would face the risk of being eliminated during early stages of infection, thus failing later transmission." (PMID 32327653, 2020).
infection (continued). "Infection of macrophages with candidalysin-deficient C. albicans mutants proved that candidalysin crucially contributes to C. albicans-dependent IL-1β secretion by murine and human macrophages." (PMID 32722029, 2020). "In contrast, IL-1β (rs16944) (GG) and IL-28 (rs8099917) GG and TG genotypes were associated with reduced risk of infection." (PMID 32161622, 2020). "Infection with RV1b for 48 h produced similar responses, with increased IL-1α and IL-1β following infection significantly associated with necrotic events only in CF AEC, but with apoptotic events in non-CF and CF AEC." (PMID 32328066, 2020). "The major role of pro-inflammatory cytokines IL-1β is to continuously recruit polymorphonuclear (PMN) neutrophils at the site of infection to effectively reduce the bacterial load this causes ALI and ARDS." (PMID 33634060, 2020). "Polymorphisms in IL-1β and its endogenous receptor antagonist affect gastric mucosal IL-1β production in response to infection of H. pylori and are associated with GC occurrence." (PMID 32123313, 2020). "Although IL-1β/MyD88 deficiency in Tregs is a common link in poor infection outcomes in our MFYcre and aging infection models, there are distinct differences between them." (PMID 33240286, 2020). "TNF-α and IL-1β both participated in the inflammation in the early stage, and they were associated with activating and recruiting neutrophils to the site of infection." (PMID 32581788, 2020). "The interleukin 1 (IL-1) cytokine family (IL-1α, IL-1β, IL-18, IL-33, IL-36α, IL-36β, and IL-36γ) acts as DAMPs and stimulates sterile inflammation caused by necrosis and increases the inflammation with infection-related tissue damage." (PMID 32184728, 2020). "It has been shown that an increase in IL-1β cytokine causes lung damage during infection by influenza A." (PMID 31196204, 2019). "Stimulation with IL-1β or infection with RV16 caused modest increases in CXCL8, while the addition of IL-1β to RV16-infected cells significantly augmented CXCL8 release." (PMID 30333178, 2019). "N. brasiliensis infection caused increased levels of pro–IL-1β within alveolar Mφs; however, this infection-induced response was unaffected by NLRP3 deficiency." (PMID 31586037, 2019). "The effect of DENV2(NGC) infection on the secretion of IL-1β was then evaluated in IFNAR–/– C57BL/6 mice deficient in IFN-α/β receptor." (PMID 31824450, 2019). "Fas−/− mice were highly susceptible to Listeria monocytogenes, an intracellular Gram-positive bacterium that causes serious food-born infections in humans, with the impaired secretion of IL-18 and IL-1β." (PMID 30717382, 2019). "The significant production of pro-inflammatory cytokine IL-1β after VSV or EMCV infection was further confirmed by enzyme-linked immunosorbent assays (ELISA) as well as the secretion of IL-18." (PMID 31024004, 2019). "In this model, neutrophils were also associated with production of cytokines (IL-1β, IL-6, and IL-10) and several chemokines that are known to mediate migration of inflammatory and immune cells to sites of infection." (PMID 31134081, 2019). "Evidence demonstrates that blockade of IL-1β signaling decreases postoperative pain, however complete blockade of IL-1β signaling increases the risk of infection and decreases effective wound healing." (PMID 31244767, 2019). "We show that bacteria expressing a functional NADase evade P2X7 activation, while infection with a NADase-deficient GAS strain leads to a P2X7-mediated increase in IL-1β." (PMID 31275321, 2019). "IL-1β is a proinflammatory cytokine that contributes to host defense against infection and is also associated with autoimmune and inflammatory diseases." (PMID 31449558, 2019). "The proinflammatory cytokine IL-1β and its antagonist IL-1RA are strongly induced by infection and are encoded by polymorphic genes." (PMID 29849489, 2018).
infection (continued). "Our previous study in a murine model of infection showed that higher basal levels of IL-1β and OPN in aged mice are associated with impaired antiviral response that leads to increased susceptibility to RSV infection." (PMID 29677209, 2018). "Hereby, bioactive IL-1β produced in response to MVA infection is effectively neutralized by the MVA encoded viral IL-1β-receptor protein." (PMID 30149505, 2018). "Cord blood infection was significantly associated with higher concentrations of IL-1β secreted by PBMC." (PMID 29743113, 2018). "So, reduced production of IL-1β in Casp11-/- and Gsdmd-/- mice is another possible mechanism to enhance susceptibility to infection." (PMID 30589883, 2018). "LC-CLA in secreting auxiliary amounts of CLA, ameliorated the ST infection-induced gut inflammatory responses by suppressing Th1 cells through reducing IL-12 and pathogenic Th17 cells through reducing IL-1β." (PMID 30443248, 2018). "NLRP3 has been widely shown to be activated during infections with pathogenic microbes by interleukin-1β (IL-1β)." (PMID 30013955, 2018). "In the context of infection, inflammasome-associated IL-1β shifts IL-6-dependent synthesis of APP to those involved in pathogen defense, including hepcidin, C-reactive protein, serum amyloid P, and serum amyloid A49." (PMID 29891920, 2018). "Previous studies showed that IL-1β can aggravate the primary damage caused by infection of the central nervous system (CNS), and IL-1β deficient mice display reduced neuronal loss and infarct volumes after ischemic brain damage in in vivo studies." (PMID 29973222, 2018). "It causes robust microglial activation, increase in IL-1β production, and inflammation that enhances the severity of infection." (PMID 29885667, 2018). "We demonstrate here that the accumulation of macrophage and monocyte at the GI wall is associated with increased inflammatory cytokines IL-1β, IL-6, TNFα and INFγ-cytokines which signal recruitment of more inflammatory cells to sites of infection." (PMID 30249047, 2018). "IL-1β has an important role in controlling infections caused by Salmonella typhimurium and Candida albicans; however, excessive amount of IL-1β is also associated with auto-inflammatory diseases." (PMID 30470758, 2018). "Transcription of genes encoding IL-1 family cytokine precursor proteins (pro-IL-1β and pro-IL-18) occurs in response to tissue injury or infection, resulting in inflammatory cytokine production via the inflammasome." (PMID 29670611, 2018). "Specifically, M1-like associated gene IL-1β was significantly increased in cells after class II strain LaSota infection, whereas M2-like associated gene IL-10 was only upregulated in class I strain F55-infected cells." (PMID 29670609, 2018). "Given that TPL-2 is downstream of TLR4 and IL-1R-signaling and that TPL-2-deficent mice are more susceptible to bacterial infection due to reduced TNFα and IL-1β secretions, we analyzed the changes in microbiota following infection of WT and Map3k8–/–mice." (PMID 28759611, 2017). "Stimulation of GECs with LPS or infection with P. gingivalis caused induction of the IL-1β gene and accumulation of IL-1β in the cells." (PMID 28056810, 2017). "MPO deficiency led to elevated pulmonary IL-1β expression in response to WT C. albicans indicating that during infection, neutrophils upregulate IL-1β production in an alternative ROS-dependent manner." (PMID 28314592, 2017). "This control was associated with IL-1β and IL-18 secretion induced by caspase-1 activity starting at an early phase of infection." (PMID 28740491, 2017). "In the conclusion, our results indicated that RIP3 deficiency can protect mice from the infection of influenza H7N9 virus by downregulating caspase 1/IL1β signaling, which provided evidence of the RIP3 involved necroptosis independent manner." (PMID 28423682, 2017).